ALB (albumin)
Diseases named in the same sentence as ALB in open-access papers (continued):
Sharing a sentence is not in itself a finding about the gene and the disease.
endothelial dysfunction (continued). "However, it has been speculated that a glomerular albumin leak reflects widespread atherosclerosis-mediated capillary vasculopathy and endothelial dysfunction, which impair endothelium-dependent vasodilation." (PMID 28006020, 2016). "Chronic intermittent hypoxia and sleep fragmentation may result in inflammation, oxidative stress and activation of the sympathetic nervous system and renin-angiotensin-aldosterone system, and, in turn, endothelial dysfunction and glomerular hypertension may increase urinary albumin excretion." (PMID 24265736, 2013). "Thus the relationship between increased albumin excretion and decreased physical activity may be explained in the context of endothelial dysfunction." (PMID 24455256, 2013). "In addition, endothelial dysfunction within the glomerular basement membrane may modify glomerular barrier permeability, thus leading to the excretion of albumin into the urine." (PMID 22686733, 2012). "Mechanistically, fT3 showed a correlation to parameters of hepatic dysfunction (i.e. MELD and albumin), PH (i.e. HVPG), endothelial dysfunction (i.e. VWF36,37), and hyperdynamic circulation (i.e. proBNP7), suggesting a role of fT3 in ACLD progression." (PMID 38125301, 2024). "Consequently, hyperinsulinemia, increased adiposity, and IR could result in developing kidney dysfunction and increased risk of CKD during a long period through the increments in glomerular hyperfiltration, endothelial dysfunction, albumin excretion, and inducing vascular permeability." (PMID 36624389, 2023). "Elevated urine albumin-creatinine ratio (UACR) is a measure of renal microvascular dysfunction, and has been suggested to be a marker of endothelial dysfunction." (PMID 34570768, 2021). "Hyperinsulinemia may induce increased albuminuria through its direct effect on glomerular hyperfiltration, endothelial dysfunction, and increased vascular permeability over the long term, although in non-diabetic subjects, even a short-term insulin infusion increases urinary albumin excretion." (PMID 34300354, 2021). "Multivariable-Adjusted Regression Coefficients (95% Confidence Intervals) of One Standard Deviation Higher Log-transformed Endothelial Dysfunction Biomarkers with Estimated-GFR and Log-transformed Urinary Albumin Excretion." (PMID 26132137, 2015). "These, in turn, can injure platelets, microcirculatory endothelial cells, and acinar cells if they are not bound by albumin, resulting in the production of inflammatory mediators, the impairment of blood flow, and overall endothelial dysfunction." (PMID 40115788, 2025). "We previously showed that HO-1 induction could increase serum adiponectin, thus reducing urinary albumin levels and protecting against OKD by improving endothelial dysfunction." (PMID 35784553, 2022). "Urine albumin-creatinine ratio (UACR) as a measure of renal microvascular endothelial dysfunction has not been previously evaluated in our novel population of women with suspected INOCA." (PMID 34570768, 2021). "Longitudinal follow-up of MA and NHW cohorts should help determine whether endothelial dysfunction, as measured by FMD, and urinary albumin provide additional value in predicting CVD outcomes in additional to traditional risk factors." (PMID 18752679, 2008). "Parameters studied were urinary albumin/creatinine ratio (UACR), biomarkers of podocyte damage (synaptopodin, podocalyxin), PT dysfunction (kidney injury molecule-1-KIM-1, N-acetyl-β-(D)-glucosaminidase-NAG), endothelial dysfunction (P-selectin), VEGF, sFlt-1, and PlGF." (PMID 42123337, 2026). "Therefore, non-early albumin administration occurs after maximal endothelial dysfunction has developed." (PMID 41468394, 2025).
endothelial dysfunction (continued). "Albumin is a negative acute phase protein, and a decrease in albumin levels leads to increased blood viscosity, endothelial dysfunction, platelet aggregation, increased oxidation of low-density lipoprotein cholesterol (LDL-C), and consequently increased foam cell formation and inflammation." (PMID 41153281, 2025). "Urinary albumin excretion can be regarded as an important indicator for assessing CVD mortality of RA populations, for reasons that may include either: 1) It reflects endothelial dysfunction or 2) It may indicate the acute phase inflammatory response." (PMID 39364405, 2024). "Albumin excretion was high in patients without AKI, perhaps because of endothelial dysfunction secondary to inflammation, a known consequence and independent predictor of mortality in critically ill patients." (PMID 25366893, 2014).
dementia (154 papers, 2007 to 2026). Loss of intellectual abilities interfering with an individual's social and occupational functions. "In this study, low TMT was associated with weight loss and low albumin levels after 24 weeks follow-up of patients at risk of dementia." (PMID 40821925, 2025). "Some studies have linked lower serum albumin levels to a higher risk of cognitive impairment and dementia." (PMID 40391213, 2025). "Our findings indicate that individuals with higher baseline serum albumin levels exhibited a significantly lower risk of developing incident dementia." (PMID 39206288, 2024). "In the current study, our results suggested that higher serum albumin level at baseline was associated with a decreased risk of dementia." (PMID 39206288, 2024). "Our analysis demonstrated that higher serum albumin levels are associated with a reduced risk of dementia." (PMID 39206288, 2024). "Our study findings suggest that higher pre-existing serum albumin levels are associated with a reduced risk of developing dementia, while elevated urine microalbumin levels are linked to an increased risk of dementia." (PMID 39206288, 2024). "Our study underscores the potential role of serum albumin as a biomarker associated with reduced dementia risk." (PMID 39206288, 2024). "After adjusting for fundamental covariates in Model 1, each standard deviation (SD) increase in serum albumin was associated with a reduced risk of incident dementia (beta = −0.024, SE = 0.004, p = 7.28E-08)." (PMID 39206288, 2024). "Our results reveal that elevated baseline serum albumin levels are linked to a decreased risk of developing dementia (beta = −0.024, SE = 0.004, p < 0.001)." (PMID 39206288, 2024). "In 202,702 participants aged ≥ 60 years from the UK Biobank, Cox proportional-hazards models were used to examine the associations between eGFR and urine albumin creatinine ratio (ACR) with risk of incident dementia." (PMID 37605228, 2023). "Higher urinary albumin to creatine ratio was associated with greater risk of cognitive impairment/dementia, whereas body weight and key lipid markers were negatively associated." (PMID 39081976, 2023). "The results for albumin, an antioxidant, was similar to that in previous studies with higher serum albumin associated with lower dementia risk." (PMID 36163029, 2022). "Each unit increase in the CSF/blood albumin index was significantly associated with an increase in the Clinical Dementia Rating–Sum of Boxes by 0.09 units (P = .015)." (PMID 36506058, 2022). "For all-cause dementia, we identified creatinine, albumin and the amino acids glutamine, leucine and tyrosine as predominant contributors to predicted risk." (PMID 36138150, 2022). "The role of albumin in Parkinson disease (PD) is not well understood, our study will investigate the association between the serum albumin level and risk of dementia, motor impairment, as well as survival outcome in PD." (PMID 36123949, 2022). "An instrument that combines SQ with four variables - age, serum albumin, presence of dementia and peripheral vascular disease - to predict the risk of death at 6, 12, or 18 months for hemodialysis patients." (PMID 32897286, 2021). "We found dementia severity was significantly associated with kidney function, serum albumin, and hemoglobin in the oldest-old with AD." (PMID 33028210, 2020). "Cox regression models were conducted analyzing the association between dementia and MA using albumin creatine ratio (ACR)." (PMID 31299931, 2019). "This is a preliminary study; more substantive research is needed to clarify the factors that cause differences in albumin and hemoglobin levels among dementia diagnostic groups." (PMID 27336725, 2016). "Several studies suggest that low albumin levels are associated with a risk for cognitive impairment and dementia." (PMID 27931194, 2016).
dementia (continued). "All previous studies examining the associations between urinary albumin excretion and cognitive performance, cognitive decline, or dementia have been performed in Caucasian populations, although some studies did include African Americans." (PMID 25530658, 2014). "Tools like aspiration pneumonia prediction models and the ADELES risk score (Age, Dementia, Eating Dependency, Leg Surgery, and Serum Albumin) for lower-extremity surgeries can support tailored discharge planning and enhance preparedness for the elderly and their families." (PMID 41029370, 2025). "Furthermore, significant interactions were observed among age, BMI, alcohol consumption, and serum albumin regarding the risk of incident dementia." (PMID 39206288, 2024). "Consequently, further research is necessary to comprehensively explore the association between albumin in urine and the risk of dementia." (PMID 39206288, 2024). "In addition, our results revealed that higher level of albumin in urine was associated with a higher risk of dementia." (PMID 39206288, 2024). "Studies have shown that low serum albumin levels are associated with an increased likelihood of both dementia and mild cognitive impairment in the elderly population after adjustment for age, gender, education, and additional risk factors for cognitive impairment." (PMID 39398776, 2024). "Age, sex, BMI, low hemoglobin level, time from injury to admission, time from injury to surgery, type of hip fracture, CHD, dementia, pulmonary disease, kidney disease, smoking, fibrinogen, C-reactive protein, and albumin were considered independent risk factors for DVT." (PMID 36615152, 2023). "However, many other risk-factors, including, WBC, creatinine, albumin levels prior to surgery, dementia, cancer etiology and blood transfusion were found to be associated with perioperative mortality in this age group." (PMID 37048549, 2023). "Whether serum albumin is a bystander along with other nutritional deficiencies in frail elderly patients which may contribute to dementia or it has an independent role in pathogenesis is yet to be determined." (PMID 36462552, 2022). "Low albumin have previously linked to increased incidence of Alzheimer's and all cause dementia." (PMID 36462552, 2022). "In addition, we correlated these cell populations with dementia-associated changes such as decreasing MMSE values as marker for the progression of the cognitive decline but also with Q Albumin." (PMID 34427746, 2022). "As inflammatory mechanisms are involved in the pathogenesis of dementia, including Alzheimer’s disease, low serum albumin levels may become a risk factor for cognitive decline in AD." (PMID 33028210, 2020). "Researchers have also considered other parameters (e.g., serum albumin, B12) but low levels may suggest an underlying clinical issue suggesting that their specific validity in the context of older individual with dementia should be evaluated." (PMID 32336948, 2020). "In the present study we addressed the question if ApoE genotypes might be associated with BBB function measured by albumin ratio (QAlb) in a large cohort of patients with different types of dementia." (PMID 24386372, 2013). "In addition to this, a previous study illustrated that fructosamine and glycated albumin (GA), as two biomarkers that could better estimate short-term (2–3 weeks) glycemic control, were associated with incident dementia." (PMID 37821909, 2023). "The variables included age, dementia, preadmission cognitive impairment, preoperative albumin, duration of the procedure, and length of hospital stay (days)." (PMID 40168626, 2025). "We observed a weak correlation of CSF PDGFRβ with the CSF/plasma albumin quotient, considered a biomarker of blood-CSF barrier integrity, driven by the dementia group, as it has already been reported." (PMID 40239464, 2025). "Some studies have reported reduced serum albumin levels in patients with different types of dementia." (PMID 38674807, 2024).
dementia (continued). "The leading causes of mortality at one year were respiratory complications, readmission, cardiac complications, the male sex, dementia, age, and lower albumin and hemoglobin levels." (PMID 38667514, 2024). "Previous research has identified advanced age, preoperative dementia, low albumin levels, diabetes, surgical delay and pain as contributors to delirium." (PMID 39835112, 2024). "It was suggested that patients with low albumin, low potassium, and dementia developed hypokalemia earlier with yokukansan administration." (PMID 38868417, 2023). "The authors identified four behavioral factors in patients with dementia related to alterations in weight and body mass index, food consumption, and low serum albumin levels." (PMID 37754622, 2023). "The SSVD and mixed dementia groups had higher CSF/serum albumin ratio than the control group, and in addition, the SSVD group had higher CSF/serum albumin ratio than the AD group." (PMID 37980667, 2023). "Our findings suggest that potassium levels must be checked early after yokukansan administration, especially in patients with low albumin, low potassium, and dementia." (PMID 38868417, 2023). "This study reports that the number of PFUs was linked to MUAC in a group of older subjects with dementia, for whom MUAC and albumin levels were highly correlated." (PMID 36429816, 2022). "The last parameter which in our study that had independent relationship with dementia was a lower serum albumin levels." (PMID 36462552, 2022). "A higher percentage of subjects on a texture-modified diet had MUAC < 21 cm, albumin levels < 35 g/L, were taking dietary supplements, and had severe dementia compared with the corresponding percentage of subjects on a normal-texture diet." (PMID 36429816, 2022). "Like in other forms of dementia, a dysfunction of the B-CSF-B, measured by Q Albumin, is also detected in FTD." (PMID 34427746, 2022). "Subsequent study has been shown that interfering with the ratio of serum bilirubin/albumin by albumin infusion improves the outcome of dementia patients with the deposition of Aβ." (PMID 34222023, 2021). "Our recent study shows that interfering the serum bilirubin/albumin concentrations in dementia patients with Aβ deposition through intravenous albumin infusion can improve their clinical outcomes." (PMID 34222023, 2021). "In the non-dementia group, on the contrary, albumin concentration was higher (56.52 ± 4.64 vs 54.90 ± 4.59, p value = 0.02)." (PMID 34674153, 2021). "Both CSF and serum NFL concentrations correlated with increasing blood-brain barrier damage measured by the CSF/serum albumin ratio, as previously shown in studies of dementias and in CNS injury in HIV." (PMID 32816287, 2020). "In this study, we first performed a cross-sectional case control study to determine the bilirubin and albumin concentrations in dementia patients with Aβ deposition." (PMID 33013289, 2020). "Consistent with these experimental and clinical findings, our intervention study shows that intravenous supplementation of human albumin at a dose of 10 g every 2 weeks for 24 weeks yields benefit on daily function and dementia severity in AD patients." (PMID 33013289, 2020). "To address this issue, we conducted a cross-sectional study to determine the effect of kidney function, serum albumin, and hemoglobin on dementia severity at the time of AD diagnosis among old people aged ≥80 years." (PMID 33028210, 2020). "Further longer studies are required to clarify the relationship between serum albumin, hemoglobin, and disease severity in the oldest old people with dementia." (PMID 33028210, 2020). "IBIL and the IBIL/ALB ratio are significantly higher in dementia patients with Aβ deposition, and intravenous administration of albumin is beneficial to AD treatment." (PMID 33013289, 2020). "Serum bilirubin and albumin concentrations were measured in three types of dementia with Aβ deposition (AD, DLB, and GPI)." (PMID 33013289, 2020).